RNU2-61P (RNA, U2 small nuclear 61, pseudogene)
Gene: Small nuclear RNA gene on chromosome 6 (89,063,500 to 89,063,690, reverse strand). Ensembl gene ENSG00000223001.
Homologues: Orthologues: chimpanzee U2 (99% identical), macaque U2 (95% identical), pig U2 (79% identical), guinea pig U2 (78% identical), rabbit U2 (72% identical), rabbit U2 (40% identical), rabbit U2 (39% identical), tropical clawed frog U2 (20% identical). Paralogues in human: RNU2-56P (86% identical), U2 (85% identical), RNU2-64P (85% identical), RNU2-14P (83% identical), RNU2-59P (83% identical), RNU2-26P (83% identical), RNU2-2 (82% identical), RNU2-57P (82% identical), RNU2-48P (82% identical), RNU2-4P (82% identical), RNU2-52P (81% identical), RNU2-32P (81% identical), and 65 more.